CDH23 (cadherin related 23)
Diseases named in the same sentence as CDH23 in open-access papers (continued):
Sharing a sentence is not in itself a finding about the gene and the disease.
age-related hearing loss (19 papers, 2010 to 2023). "As both parental strains carry Cdh23 mutations, which are associated with age-related hearing loss, we used isogenic wild-type ESC controls to account for any potential phenotype caused by the background genetics." (PMID 37745294, 2023). "This includes the presence of a variant allele in the Cdh23 gene, which is associated with age-related hearing loss (ARHL)." (PMID 38131808, 2023). "Unfortunately, C57BL/6 mice, a strain widely used for transgenic manipulation, display age-related hearing loss (AHL) because of an inbred mutation in the Cadherin 23 gene (Cdh23) that affects hair cell mechanotransduction." (PMID 35473764, 2022). "A 753G>A polymorphism in Cdh23 (chr10: 59,993,653 bp) has previously been implicated in age-related hearing loss in C57BL/6J, DBA/2J, and other inbred strains." (PMID 20628639, 2010). "Actually, CDH23 mutations have been reported as responsible for age-related hearing loss in mice." (PMID 22899989, 2012). "Methylated DNA quantification revealed 3.27-fold increase in methylation levels at common CpG island of CDH23 in blood samples from women with presbycusis as compared to controls." (PMID 30131691, 2018). "Materials and Methods: We screened for methylation changes in this particular position for CDH23 gene in 50 blood samples of elderly women affected with presbycusis and healthy control cohort." (PMID 30131691, 2018). "For example, C57BL/6 mice carry the Ahl allele of Cdh23 which predisposes them to early onset presbycusis and is therefore not always an ideal choice for auditory research." (PMID 34722533, 2021). "High thresholds in response to 48 kHz tones were observed in mice of all three genotypes and likely reflected the effects of the Cdh23 allele in the C57BL/6 background, which predisposes many inbred strains to age-related hearing loss (ARHL) that typically initiates at high frequencies." (PMID 30157177, 2018). "Significantly late onset age of SNHL in SB116 might also increase the possibility of a relationship between CDH23 and presbycusis in an older population." (PMID 27792758, 2016).
retinitis pigmentosa (15 papers, 2011 to 2024). Retinitis pigmentosa (RP) is an inherited retinal dystrophy leading to progressive loss of the photoreceptors and retinal pigment epithelium and resulting in blindness usually after several decades. "Genotype (variant combinations) and phenotype (association with retinal pigmentosa, onset age) are shown to be well correlated and are thought to be related to the residual function defined by the CDH23 variants." (PMID 35020051, 2022). "After evaluating with this test, 16 known variants were detected in 16 individuals in whom four showed retinitis pigmentosa (RP) and hearing loss with homozygous and compound heterozygous variants in MYO7A, CDH23 and USH2A genes." (PMID 31850270, 2019). "Four patients had retinitis pigmentosa (RP) with HL in three causative genes, MYO7A, CDH23 and USH2A, with novel and known variants." (PMID 31850270, 2019). "Mutations in MYO7A, USH1C, CDH23, PCDH15 and WHRN have also been reported in patients affected by hearing impairment only, while USH2A is also involved in isolated retinitis pigmentosa." (PMID 21569298, 2011). "Mutations in four cadherin, namely CDHR1, CDH23, PCDH15, CDH3, the latter being the dominant RPE cadherin, have been identified as causes of inherited retinal degeneration, including cone-rod dystrophy, macular dystrophy and Retinitis Pigmentosa." (PMID 36645183, 2023). "We then tested whether subretinal administration of triple AAV2/8 vectors results in expression of CDH23 and ALMS1, which are both mutated in syndromic forms of retinitis pigmentosa." (PMID 29292161, 2018).
nonsyndromic deafness (10 papers, 2008 to 2025). An auditory system disease that is associated with permanent hearing loss caused by damage to structures in the inner ear and/or the middle ear, which is not associated with other signs and symptoms. "Previous study showed that pathogenic CDH23 are variants responsible for both recessive DFNB12 nonsyndromic hearing loss (NSHL) and Usher syndrome 1D (USH1D)." (PMID 37575969, 2023). "Nonsyndromic deafness is associated with CDH23 missense variants that are presumed to be hypomorphic alleles with sufficient residual activity for retinal function but not for auditory cochlear function." (PMID 32795431, 2021). "In humans, some cadherin 23 (CDH23) missense mutations cause nonsyndromic deafness (DFNB12), whereas truncating nonsense, frameshift, and splice site mutations have been reported to cause USH1D." (PMID 19756182, 2009). "A large number of pathogenic recessive mutant alleles of CDH23 have been described that are associated with USH1 or nonsyndromic deafness DFNB12." (PMID 19057657, 2008). "CDH23 (OMIM ID: *605516) is causative for autosomal recessive Usher syndrome type 1D (USH1D) and non-syndromic deafness DFNB12." (PMID 40121402, 2025).
autosomal recessive deafness (9 papers, 2010 to 2024). "Our findings significantly expanded the mutation spectrum of CDH23-associated autosomal recessive hearing loss." (PMID 36468022, 2022). "However, some studies from the United States, Belgium, Northern Europe, and East Asia indicated that pathogenic variants in SLC26A4, MYO15A, OTOF, and CDH23 are probably the most common causes of autosomal recessive hearing loss, after the exclusion of variants in the DFNB1 locus." (PMID 39498320, 2024).
breast carcinoma (8 papers, 2012 to 2025). "This gene has been reported to play a role in early stages of tumor metastasis through regulation of cell-cell adhesion, and upregulation of CDH23 gene may be associated with breast cancer." (PMID 36352452, 2022). "Similarly, in ST09 treatment, the gene hypermethylated and overexpressed was CDH23, cadherin 23, and mutations in this gene have been found in younger breast cancer patients." (PMID 36474139, 2022). "CDH23 is also upregulated in breast cancer cells, and it participates in cell adhesion and play a role in the early stages of metastasis." (PMID 39744166, 2025). "CDH23 participates in cell adhesion and its expression is upregulated in breast cancer cells 11, 12, and the strong propensity of CDH23 for aggregation inhibits cell migration in lung adenocarcinoma cells." (PMID 39744166, 2025). "Similar to classical cadherins, the localization of CDH23 at the cell-cell junction was showed in breast cancer cell MCF7 in vitro." (PMID 34252883, 2021). "Previous studies showed that CDH23 was up-regulated in breast cancer tissues and was involved in metastatic processes." (PMID 26756918, 2016).
Blindness (7 papers, 2016 to 2024). Blindness is the condition of lacking visual perception defined as a profound reduction in visual perception. "USH1D patients who carry different mutations of the same gene (Cdh23) as DFNB12 exhibit congenital deafness and postnatal-onset blindness." (PMID 27882946, 2016). "These variants were considered less likely associated with the phenotype because the variant alleles in CDH23 and DTHD1_144 were detected in unrelated black-footed cats that have not been interbred with the lineage that segregates for vision impairment." (PMID 28322220, 2017).
retinal degeneration (5 papers, 2008 to 2023). Degeneration of the retina. "In situ hybridization and immunohistochemistry were used to characterize cdh23 expression in the zebrafish, and to evaluate cdh23 mutants for retinal degeneration." (PMID 22977299, 2012). "Most of the reported mutations of mouse Cdh23 cause the waltzer phenotype, which is deafness and vestibular dysfunction but no retinal degeneration." (PMID 19756182, 2009). "Moreover, larvae with mutations in cdh23 do not exhibit any signs of gross retinal degeneration or dysfunction." (PMID 22977299, 2012). "We compared cadherin 23 (Cdh23) mRNA and protein variants in the inner ear and retina of wild-type and mutant mice and primates to better understand the pleiotropic effects of Cdh23 mutations, and specifically to understand the absence of retinal degeneration in Cdh23 mutant mice." (PMID 19756182, 2009). "Mouse models of the USH1 genes (Myo7a, shaker 1; Ush1c, deaf circler; Cdh23, waltzer; Pcdh15, Ames waltzer; Sans, Jackson shaker) exhibit circling behavior, head tossing and profound sensorineural hearing loss, but do not exhibit retinal degeneration." (PMID 19057657, 2008). "We predict that the defects caused by these two alleles likely do not contribute to gross retinal degeneration or disorganization, but may instead contribute to subtle defects that would require more careful analysis of the cdh23-positive amacrine cell population in isolation." (PMID 22977299, 2012). "Should this explanation prove to be correct for the absence of retinal degeneration in v and av mutant mice, then increasing the levels of particular isoforms of CDH23 and PCDH15 in the mutant human retina might delay the onset or perhaps retard the progress of the RP component of USH1." (PMID 19057657, 2008).
schizophrenia (5 papers, 2021 to 2025). A major psychotic disorder characterized by abnormalities in the perception or expression of reality. "The variants c.753G>A and c.5985C>A in CDH23 have been associated with schizophrenia in recent studies." (PMID 39017633, 2024). "The potential PPI QTL gene, Fabp7, is associated with functional links to the NMDA receptor; further analysis, using engineered mice and human pluripotent stem cells, revealed a potential role of Cdh23 in PPI and CDH23 in schizophrenia." (PMID 41153356, 2025). "CDH23 is a known USH type 1 causative gene, recently associated with schizophrenia-like symptoms and bipolar disorders." (PMID 38131811, 2023). "Specifically, in the “schizophrenia-female” group, we observed a significantly higher incidence of the rs6265-T (V66M) variant in the BDNF gene (p = 0.0180, n = 47) and a lower occurrence of the rs1227051-A variant in the CDH23 gene (p = 0.0495, n = 47) compared to healthy volunteers." (PMID 38699454, 2024).
lung carcinoma (4 papers, 2019 to 2022). "Besides, analysis of lung cancer patient data indicated that cadherin related 23 (CDH23) – a member of the cadherin superfamily, whose genes encode calcium-dependent cell-cell adhesion glycoproteins – is downregulated in lung cancer, working as a suppressor of cell migration." (PMID 34870316, 2022). "According to previous reports, CDH23, as a cell migration inhibitor, relaxed the adhesion ability of lung cancer cells through competitive binding and was negatively correlated with cancer metastasis." (PMID 36263430, 2022). "The fusions HLA‐DPB2‐HLA‐DRB1 and CDH23‐HLA‐DPB1 were both annotated as lung cancer fusion in the FusionCancer database." (PMID 30903738, 2019). "Cdh23 proteins were also expressed in IHC of human TMA slides of lung cancer (LC) and esophageal squamous cell carcinoma (ESCC) at the cell boundaries in both healthy and cancer tissues." (PMID 30747484, 2019).
pituitary adenomas (4 papers, 2019 to 2022). "Germline mutations in CDH23 have also recently been identified and associated with both familial and sporadic pituitary adenomas." (PMID 32425987, 2020). "In a study that linked mutations in CDH23 with familial and sporadic pituitary adenomas, it was suggested that these genetic alterations could play important roles in the pathogenesis of CD." (PMID 36359740, 2022). "Furthermore, despite being reported that mutations in CDH23 are commonly observed in hearing impairment conditions, they have also been associated with pituitary adenomas." (PMID 32276436, 2020).
sensorineural hearing loss (4 papers, 2024 to 2025). "In this study, we report 2 novel variants of CDH23 in the Chinese population, providing a new example of severe sensorineural hearing loss caused by CDH23 mutations." (PMID 39287240, 2024). "USH1D has been well characterized from a hearing loss perspective and variants in CDH23 have been identified as a major cause of non-syndromic sensorineural hearing loss." (PMID 39017633, 2024).
somatotroph adenomas (4 papers, 2020 to 2025). "CDH23 (cadherin-related 23) mutations are associated with sporadic PitNET in 12% of cases, mainly with somatotroph adenomas." (PMID 40362297, 2025). "Cadherin-related 23 (CDH23) is also associated most frequently with somatotroph adenomas." (PMID 40299639, 2025). "Of the CDH23-mutated PAs, somatotroph adenomas account for the highest proportion (25.9%)." (PMID 33574795, 2020).
acute myeloid leukemia (2 papers, 2022 to 2025). Acute myeloid leukemia (AML) is a group of neoplasms arising from precursor cells committed to the myeloid cell-line differentiation. "However, the biological functions and effect of CDH23 expression on the prognosis of patients with acute myeloid leukemia (AML) are unexplored." (PMID 35597916, 2022).
Alzheimer disease (2 papers, 2016 to 2022). A progressive, neurodegenerative disease characterized by loss of function and death of nerve cells in several areas of the brain leading to loss of cognitive function such as memory and language. "In addition, synonymous variants in 4 genes [(Cadherin Related 23 (CDH23), SLC9A3 Regulator 1 (SLC9A3R1), Rhomboid Domain Containing 2 (RHBDD2), and Inter-Alpha-Trypsin Inhibitor Heavy Chain 2 (ITIH2)] linked with alzheimer's disease warrant comprehensive scrutiny of genetic variations." (PMID 36434531, 2022).
cervical cancer (2 papers, 2013 to 2019). A primary or metastatic malignant neoplasm involving the cervix. "Interestingly, independent analysis of the TCGA data by THPA also revealed the strong connection of cancer metastasis and patient survival with Cdh23 expression in cervical cancer (CESC), uterine cancer (UCEC), and skin cancer (SKCM), in addition to LUAD and ESCC." (PMID 30747484, 2019). "Among the 49 PRC2 targets (defined by consistent hyper-MVPs) identified here were 10 genes of the cadherin superfamily in HPV+ HNSCC, including CDH8 and CDH13 (both also hypermethylated in cervical cancer, CDH18, CDH19, CDH23, PCDH10, PCDH15, PCDHB1, PCDHB4, and PCDHB15." (PMID 23419152, 2013).
depression (2 papers, 2021 to 2024). "Additionally, there was a significantly increased prevalence of heterozygous variants rs1227051-G/A in the CDH23 gene (p = 0.0014, n = 79) and rs12500437-G/T in the DCHS2 gene (p = 0.0390, n = 79) in the “depression” group." (PMID 38699454, 2024).
diffuse large B-cell lymphoma (2 papers, 2021 to 2025). "Additionally, the decreased expression of CDH23 due to DNA methylation is linked to a poor prognosis in diffuse large B-cell lymphoma (DLBCL)." (PMID 40299416, 2025). "However, the epigenetic regulation, the biological functions, the mechanisms and the prognostic value of CDH23 in diffuse large B-cell lymphoma (DLBCL) are still unclear." (PMID 34252883, 2021).
esophageal squamous cell carcinoma (2 papers, 2019 to 2021). Esophageal squamous cell carcinoma (ESCC) is a type of esophageal carcinoma (EC) that can affect any part of the esophagus, but is usually located in the upper or middle third. "CDH23 proteins were also expressed in esophageal squamous cell carcinoma (ESCC) and human lung cancer (LC) at the cell boundaries in both cancer and normal tissues." (PMID 34252883, 2021).
pancreatic cancer (2 papers, 2025). "High levels of CDH23 in pancreatic cancer patients are associated with shorter overall survival and correlated with local recurrence and distant metastasis." (PMID 41373844, 2025). "Our clinical data showed a poorer prognosis for pancreatic cancer patients with high levels of CDH23 expression, and CDH23 expression was associated with local recurrence and distant metastasis." (PMID 39744166, 2025). "When CDH23 expression was downregulated in pancreatic cancer cells by siRNA, their viability in floating culture conditions decreased sharply, and high CDH23 expression seems more likely to form cell clusters." (PMID 39744166, 2025). "In this study, we detected the expression of CDH23 in pancreatic cancer and explored the impact of CDH23 on tumor development." (PMID 39744166, 2025). "This study investigated the role and mechanism of Cadherin 23 (CDH23) action in the viability of pancreatic cancer cells." (PMID 39744166, 2025). "The viability of pancreatic cancer cells in floating culture conditions decreased sharply when CDH23 was silenced." (PMID 39744166, 2025). "The expression of CDH23 in pancreatic cancer cell lines (Panc-1, SUIT-2, MIA PaCa-2, CFPAC-1, Capan-2) was higher than that in normal pancreatic epithelial cells (HPDE cells)." (PMID 39744166, 2025). "CDH23 expression in pancreatic cancer patients and cell lines was examined using immunohistochemistry and western blotting." (PMID 39744166, 2025). "To investigate the effect of CDH23 expression in pancreatic cancer cells, we stably downregulated CDH23 expression by siRNA in SUIT-2 and CFPAC-1 cells and confirmed downregulation at both mRNA and protein levels." (PMID 39744166, 2025). "In this study, we investigated a potential function for CDH23 in pancreatic tumors by assessing CDH expression in pancreatic ductal adenocarcinoma (PDAC) cell lines and tissue samples." (PMID 39744166, 2025). "This study also analyzed the molecular mechanism of CDH23 action on pancreatic cancer cell lines." (PMID 39744166, 2025). "We found that the expression of CDH23 affects the progression and prognosis of pancreatic cancer." (PMID 39744166, 2025). "Furthermore, we silenced CDH23 expression in pancreatic cancer cell lines (Panc-1, SUIT-2, MIA PaCa-2, CFPAC-1, and Capan-2) and assessed the viability of these cells." (PMID 39744166, 2025). "Therefore, CDH23 may affect the viability of floating cells by regulating cell adhesion, thus promoting the metastasis and progression of pancreatic cancer." (PMID 39744166, 2025). "Therefore, CDH23 may promote the viability of pancreatic cancer cells through Akt signal." (PMID 39744166, 2025). "The viability and migration of pancreatic cancer cells in monolayer culture conditions did not change when CDH23 was silenced." (PMID 39744166, 2025). "In this study, we found that CHD23 promotes pancreatic cancer cells viability under the floating culture conditions but not under the monolayer culture conditions, and high CDH23 expression is more likely to promote the formation of cell clusters." (PMID 39744166, 2025).
Parkinson disease (2 papers, 2016 to 2024). A progressive degenerative disorder of the central nervous system characterized by loss of dopamine producing neurons in the substantia nigra and the presence of Lewy bodies in the substantia nigra and locus coeruleus. "In the 8 DLB patients with variants in any of the three CDH23 locations (rs181275139, rs563688802, and rs137937502), visual hallucinations were present in 62.5% (n = 5), Parkinsonism in 37.5% (n = 3), fluctuation in 37.5% (n = 3), and RBD in 12.5% (n = 1)." (PMID 39572598, 2024).
pituitary tumor (2 papers, 2022). A benign or malignant neoplasm affecting the pituitary gland. "Most importantly, PCDH15 has been shown to interact with cadherin-related 23 (CDH23), which has been implicated in sporadic and familial forms of pituitary tumors." (PMID 36233050, 2022).
cardiomyopathy (1 paper, 2025). A disease of the heart muscle or myocardium proper. "Furthermore, 2 of the 46 cardiomyopathy genes, CDH23 and myosin binding protein C (MYBPC3), were significantly enriched for rare functional coding variants, as revealed by mutation burden analysis." (PMID 39730912, 2025).